CPS1 (carbamoyl-phosphate synthase 1)
Diseases named in the same sentence as CPS1 in open-access papers (continued):
Sharing a sentence is not in itself a finding about the gene and the disease.
tumor (continued). "In contrast, CPS1 expression dramatically increased in a significant portion of metastatic lung tumors, indicating that the urea cycle underwent metabolic reprogramming and activation in these tumor cells." (PMID 41356199, 2026). "This compelling evidence shows that CPS1 inhibitor can indeed reduce tumor metastasis." (PMID 41356199, 2026). "We also found that the hostile tumor microenvironment (TME), such as hypoxia, acidosis and nutrition deprivation, could cause the downregulation of CPS1, which might be mediated by the ER stress response." (PMID 39387452, 2024). "The clinical characteristics of CPS1 and the analysis of mice in situ liver tumor model hinted CPS1 might have double‐faced role in HCC as knocking down CPS1 led to reduce tumor volume but increase the number of metastatic foci." (PMID 39387452, 2024). "Subcutaneous transplantation of tumor cells revealed the proliferative effect of CPS1 in vivo." (PMID 39387452, 2024). "This study used data mining to assess whether the aberrant expression of NAGS and biosynthesis of NAG can explain the increased activity of CPS1 that contributes to higher de novo pyrimidine production and tumor cell proliferation." (PMID 37047726, 2023). "There was little overlap between NAGS, CPS1, and citrin sequence variants found in patients with respective deficiencies, tumor samples, and individuals without known rare genetic diseases." (PMID 37047726, 2023). "The discrepancies of CPS1 expression between two groups of cancers may be due to different mechanisms in tumorigenesis and tumor progression." (PMID 37443694, 2023). "Furthermore, we analyzed clinicopathological parameters and found that lower expression of CPS1 in IHCCs was prominently related to more advanced primary tumor (pT1, pT2 and pT3) with statistical significance (p = 0.003)." (PMID 37443694, 2023). "However, the overexpression of the converting enzyme, carbamoyl-phosphate synthetase 1(CPS1), has been found to encourage pyrimidine biosynthesis, which is then connected to tumor proliferation." (PMID 36419080, 2022). "We propose that ASS1 and CPS1 might be necessary for hepatocellular tumorigenesis and early-stage cancer to detoxify, but reduce in the advanced stage when tumor cells are faced with hostile microenvironment." (PMID 35655758, 2022). "We constructed a novel seven-gene signature (B3GALT5-AS1, DNER, CSN1S1, KIF5A, SIX3, NOTUM, and CPS1) and a combined prognostic model integrating a seven-gene signature with patient age and tumor size to quantify the likelihood of distant metastasis in lymph node-negative TNBC." (PMID 34604089, 2021). "Furthermore, we demonstrated that CPS1 protein is further downregulated during tumor progression, such as in recurrent tumors and distant metastases." (PMID 33670206, 2021). "In this line, tumors with microvascular invasion and G3 tumor grade showed lower CPS1 levels." (PMID 33670206, 2021). "Similarly, CPS1 expression was low or negative in circulating tumor cells (CTCs) of HCC patients and negatively associated with EpCAM expression." (PMID 39387452, 2024). "Therefore, it is possible that NCG of microbial origin can activate CPS1 in tumor cells." (PMID 37047726, 2023). "As both dysregulation of CAD and CPS1 have been shown to result in urea cycle dysregulation, we hypothesized that combining CAD and CPS1 scores would improve prognostic prediction, as alterations in both enzymes should result in additive biological effects beneficial to tumor growth." (PMID 33670206, 2021). "This stemness-associated signature integrates developmental drivers such as PTPRH, AHNAK2, PCDH7, metabolic regulators CPS1, SFTPB, and hypoxia-responsive factors such as TCN1, TMPRSS11E, reflecting the multifaceted nature of OSA-induced tumor evolution." (PMID 41584048, 2026).
tumor (continued). "It is found that CPS1 is low‐expressed in HCC tissues and circulating tumor cells, negatively correlated with HCC stage and prognosis." (PMID 39387452, 2024). "The correlation between NAGS and CPS1, citrin and NAGS, and CPS1 and citrin mRNA expression in individual tumor samples was either weak or negligible." (PMID 37047726, 2023). "The expression of MAP2, DYNC1H1, and MKI67 was obviously higher expressed in tumor tissues, while CPS1 and PTPRB were downregulated in tumor tissues compared with normal tissues in TCGA dataset." (PMID 35311113, 2022). "Quantitative real-time PCR (qRT-PCR) exhibited that expression of CPS1 and PTPRB was downregulated in tumor tissues compared with paracancerous tissues, while MAP2, DYNC1H1, and MKI67 were overexpressed in tumor tissues." (PMID 35311113, 2022). "CPS1 knockdown in LUAD inhibits the JAK/STAT pathway, which is involved in tumor proliferation, differentiation, apoptosis, and immune regulation." (PMID 36553562, 2022). "ITGA8 and ADAMTS8 were downregulated in tumor tissues, whereas FERMT1, CTSV, CPS1, ENTPD2, SERPINB5, and LYPD3 were upregulated in tumor tissues." (PMID 35557945, 2022). "CPS1, one of the NTS downstream factors identified in the current study, is the rate-limiting enzyme in urea cycle and promotes proliferation and tumor growth." (PMID 33493519, 2021). "Subsequently, we compared the expression of mRNA levels of CPS1 and TRIP6 with their protein levels in representative sets of control ovarian tissues and EOC tumor samples divided into EOC low and high mRNA expression groups." (PMID 35008510, 2021). "Subsequently, we compared the mRNA level of ABCC3, CPS1, and TRIP6 genes in EOC tumor samples with control ovarian tissues." (PMID 35008510, 2021). "In the five-gene signatures in the ceRNA network, the expression levels of DEPDC1, CPS1, COL9A3, and PTPN21 were significantly different between early- and advanced-stage tumor tissues." (PMID 34855841, 2021). "Consistently, all the six DEGs (GLS2, ASS1, FOLH1B, AGXT2, CPS1, and GPT2) enriched in “arginine biosynthesis” in our results were significantly downregulated in tumor hepatic tissue from HBV-infected patients compared with adjacent nontumor tissues." (PMID 32775402, 2020). "miRNAs modulate the expression of numerous metabolic factors and enzymes, such as SREBF2, AKT2, G6PD, CPS1, FADS1, and ETNK1, which alter tumor cell responses to chemotherapeutic treatments." (PMID 27861141, 2016). "Because TET2 inhibition impairs PD-L1 transcription and confers tumor resistance to immunotherapy 29, we investigated whether augmenting TET activity through CPS1 inhibition enhances programmed death-ligand 1 (PD-L1) expression." (PMID 41356199, 2026). "Mechanistically, analysis of tumor tissues from these mice revealed an increase in mRNA expression of miR200 family members and a decrease in the mRNA expression of the EMT transcription factors following CPS1 knockdown." (PMID 41356199, 2026). "Immunohistochemistry (IHC) staining showed that while the UCEs CPS1, ASS1, ASL, and ARG1 were highly expressed in the periportal (zone 1) and midzonal areas (zone 2) in healthy control mice, they were expressed at various levels in the end-stage tumor tissues." (PMID 41512056, 2026). "Combined metabolic intervention: The combination of CPS1 inhibitors and GLS inhibitors may simultaneously disrupt tumor ammonia detoxification barriers and alleviate ammonia toxicity in CD8+ T cells." (PMID 41041303, 2025). "We demonstrated that negative CPS1 expression in HCC tissues or CTCs correlated with advanced tumor stage." (PMID 39387452, 2024). "Negative expression of CPS1 in HCC was correlated with advanced tumor stage and poor patient prognosis." (PMID 39387452, 2024).
tumor (continued). "There was little overlap between somatic sequence variants found in tumor samples and germline sequence variants found in patients with NAGS, CPS1, and citrin deficiencies, and in individuals without rare genetic diseases." (PMID 37047726, 2023). "Among them, ARG1 and CPS1 genes exhibit the most significant down-regulation, whose log2 ratios by comparison between IHCC and non-tumor, as well as IHCC and normal bile duct, are −4.0505 and −2.9184 (p ≤ 0.0001) and −3.9435 and −2.8787 (p ≤ 0.0002), respectively." (PMID 37443694, 2023). "We queried repositories of tumor genomic data to determine whether the higher expression of NAGS, CPS1, and citrin genes correlate with unfavorable patient outcomes." (PMID 37047726, 2023). "The results showed that both mRNA and protein of SMS were highly expressed in tumor tissues, while CPS1 was not significantly different in mRNA and protein levels." (PMID 37709932, 2023). "Note, forced expression of CPS1 induced cell proliferation and the observed repression in human HCC may simply be the result of genomic instability as was observed in tumour cells." (PMID 25872475, 2015). "By contrast, CPS1, a key enzyme in the urea cycle, and SELENOK, a regulator of ER-associated protein degradation and redox homeostasis, were largely absent or only weakly expressed in tumor sections." (PMID 41584048, 2026). "Furthermore, tumours without KRAS gene mutation show overexpression of ALDOB and CPS1 and downregulation of PGAM4 genes, which are involved in metabolic pathways such as biosynthesis of amino acids, gluconeogenesis, glycolysis and carbon metabolism." (PMID 31949199, 2020). "Therefore, we compared the types of NAGS, CPS1, and citrin sequence variants found in all tumor samples with sequence variants found in individuals without known rare diseases, and patients with NAGS, CPS1, or citrin deficiencies to increase the power of comparison." (PMID 37047726, 2023). "The other four genes (CPS1, COL12A1, EIF3H, and NBR1) were not upregulated in the tumour region of MSSCC." (PMID 21847129, 2011). "All these results suggest that some tumor cells express low or no CPS1 or P-CK, staining with CPS1 or P-CK antibody alone may miss some HCC cells, and anti-CPS1 combined with anti-P-CK antibodies may identify more HCC cells than a single antibody." (PMID 24763545, 2014).
cancer (43 papers, 2011 to 2026). A tumor composed of atypical neoplastic, often pleomorphic cells that invade other tissues. "Carbamoyl phosphate synthase 1 (CPS1) converts ammonia into carbamoyl phosphate, and the expression of this urea cycle enzyme is altered in cancers and is associated with prognosis." (PMID 41374967, 2025). "CPS1 overexpression has been linked to poor prognosis in various types of cancer, including colorectal, cholangiocarcinoma, glioblastoma, lung adenocarcinoma, and non-small cell lung cancer (NSCLC)." (PMID 37601653, 2023). "Overexpression of CPS1 is usually associated with adverse clinical outcome in patients with these cancer types." (PMID 37443694, 2023). "For example, while CPS1 promotes tumorigenesis by maintaining the pyrimidine pool in certain cancer types, it has been shown that CPS1 deficiency can lead to increased fatty acid oxidation and decreased Asp level hence elevated diacylglycerol (DAG)–protein kinase C (PKC) pathway." (PMID 41512056, 2026). "Mechanistically, CPS1 overexpression in metastatic cancer cells resulted in excessive fumarate production, an intermediate metabolite in the urea cycle." (PMID 41356199, 2026). "Given that epithelial-mesenchymal transition (EMT) drives cancer cell migration and spreading, we investigated the role of CPS1 in this process." (PMID 41356199, 2026). "Although its primary role is detoxification of ammonia in the liver 9, CPS1 is also detected in various cancers." (PMID 41356199, 2026). "The production of urea cycle enzymes ARG1 and CPS1 was below detection levels in both cancers which is in accordance with the observations published by other authors." (PMID 40963742, 2025). "Cancer cells can exploit mitochondrial pools of CP generated by the CPS1 enzyme for de novo pyrimidine biosynthesis." (PMID 40710547, 2025). "Since CPS1 has such an important anti‐cancer effect, we want to know if this gene has clinical application value." (PMID 39387452, 2024). "The lncRNA CPS1 Intronic Transcript 1 (CPS1-IT1) was recently described as a tumor suppressor in different cancer types." (PMID 35159386, 2022). "Carbamoyl-phosphate synthetase 1 (CPS1) not only serves as a crucial catalyst in the urea cycle but also functions in the progression of cancer." (PMID 35557945, 2022). "In cancer, CPS1 overexpression supports pyrimidine synthesis to promote sustained cell growth or to prevent the build-up of toxic levels of intra-tumoral ammonia." (PMID 36064721, 2022). "High expression of CPS1, FGG, and GPX2 has been frequently associated with poor prognosis of various cancers." (PMID 33493519, 2021). "CPS1, a key enzyme in the urea cycle, is highly expressed in different types of cancers and promotes cell proliferation and metastasis." (PMID 34307121, 2021). "Our results showed that except for HL-7702, some cancer cells also express CPS1, which in PLC/PRF/5, HepG2 and HLE were even higher than HL-7702." (PMID 33869206, 2021). "Based on our results, we can suggest ABCC3 and CPS1 for further investigations as potential therapeutic targets in human cancers." (PMID 35008510, 2021). "Taken together, these data indicate that the ability to metabolize ammonia into urea in cancer cells marginally depends on the expression of CPS1." (PMID 33869206, 2021).
cancer (continued). "NTS is highly positively correlated with the expression of the cancer-promoting factors CPS1, FGG, and GPX2 in a subgroup of NSCLC." (PMID 33493519, 2021). "Furthermore, we found that MMP1/CCL5/ ALDH1A3, which have been identified as cancer‐promoting genes, were the downstream targets of the CPS1/PC‐PLC/DAG/PKC axis." (PMID 39387452, 2024). "Since there has been study suggesting the use of CPS1 inhibitor to treat cancer, detecting the level of carbamoyl-phosphate, especially with spatial information, could be helpful in finding potential biomarkers or in future drug testing." (PMID 36419080, 2022). "Based on the findings of this study, OGT inhibitors might be an alternative or adjunctive treatment for cancers with CPS1 overexpression." (PMID 36064721, 2022). "CPS1, the first-rate limiting enzyme, is upregulated in a subset of non-small cell lung cancer cells and support the biosynthesis of pyrimidines and promote cancer cell proliferation." (PMID 35655758, 2022). "Moreover, unsupervised clustering analysis revealed significant positive correlation among the expression of NTS and the cancer promoting factors, such as carbamoyl phosphate synthetase 1 (CPS1) in a subgroup of NSCLC." (PMID 33493519, 2021). "The urea metabolism in cancer cells marginally depended on the expression of CPS1." (PMID 33869206, 2021). "The association of CPS1 deregulation with cancer therapy response is not known yet." (PMID 35008510, 2021). "Moreover, we found urea excretion marginally depended on the expression of CPS1 in cancer cells." (PMID 33869206, 2021). "The urea metabolism in cancer cells might marginally depend on the expression of CPS1." (PMID 33869206, 2021). "CPS1 could play a different role depending on the type of cancer cells." (PMID 31248089, 2019). "However, in cancers of non-small intestinal origin, CPS1 expression is totally lost." (PMID 31248089, 2019). "In parallel, growing evidence shows that cancer cells hijack these same mitochondrial programs to fuel anabolic growth and redox balance, often through rewiring of enzymes such as GLS2, GLUD1, or CPS1." (PMID 40710547, 2025). "The rest of the urea cycle enzymes, CPS1 and OTC are studied to a lesser extent in cancer and immune cells." (PMID 37274280, 2023). "By this strategy, CTCs with positive ASGPR and CPS1 were detected in 29/32 (91%) of HCC patients, nevertheless, no CTCs were found in healthy volunteers, benign liver diseases and other cancer groups." (PMID 36091119, 2022). "In our previous publications, we reported several new molecules potentially involved in the resistance of cancer cells to taxanes, such as ABCC3, CPS1, and TRIP6." (PMID 35008510, 2021). "Reduction in CPS1 increased shunting of glutamine to CAD, making it easier for the de novo pyrimidine pathway to participate in cancer cell proliferation." (PMID 34638594, 2021). "The key enzymes of the urea cycle, Carbamoyl-phosphate synthase 1 (CPS1), Ornithine carbamoyl-transferase (OTC), and Arginase (ARG1) were highly expressed in the liver, but normal tissues were significantly higher than cancer tissues in most cases." (PMID 33869206, 2021). "And the expression of key enzymes CPS1, OTC, ARG1 in the urea cycle were lower than normal tissue in HCC and other cancers." (PMID 33869206, 2021). "But the key enzymes of the urea cycle, especially CPS1, were often low expressed in HCC and other cancer tissues." (PMID 33869206, 2021). "A few genes were found to be in both the cancer grading and staging signatures, such as CPS1, DES, GFRA3, TMED6 and DPT, indicating some biological relevance between cancer differentiation and progression." (PMID 21445269, 2011). "Patients were categorized as metastatic (M1) or non-metastatic (M0), and significantly increased CPS1 mRNA was observed in primary cancer tissues of M1 patients." (PMID 41356199, 2026).